METTL3 (methyltransferase 3, N6-adenosine-methyltransferase complex catalytic subunit)
Diseases named in the same sentence as METTL3 in open-access papers (continued):
Sharing a sentence is not in itself a finding about the gene and the disease.
pancreatic cancer (129 papers, 2018 to 2026). "In the treatment of pancreatic cancer, previous studies have found that Mettl3 is associated with radiotherapy and chemotherapy resistance of pancreatic cancer." (PMID 41517663, 2026). "To investigate the regulatory mechanisms underlying METTL3 upregulation in pancreatic cancer, we isolated METTL3-associated protein complexes from pancreatic cancer cells by co-IP assay." (PMID 40175350, 2025). "Our previous studies have demonstrated that high expression of METTL3 is associated with a poor prognosis in pancreatic cancer and promotes the progression of pancreatic cancer cells." (PMID 40495163, 2025). "In summary, we have elucidated the molecular mechanism underlying METTL3-mediated regulation of ferroptosis and gemcitabine resistance in pancreatic cancer." (PMID 40495163, 2025). "To validate the interaction between METTL3 and TRIM21, we transfected pancreatic cancer cells with a Flag-tagged METTL3 expression vector or a vector encoding His-tagged TRIM21." (PMID 40175350, 2025). "To further elucidate the molecular mechanism underlying METTL3-mediated regulation of pancreatic cancer progression, we retrieved the GSE146806 and GSE132306 datasets from the GEO database." (PMID 40495163, 2025). "To further explore the impact of m6A genes on pancreatic cancer prognosis, we conducted transcriptomic analyses and identified METTL3 and METTL16 as the key m6A ‘writer’ genes associated with better patient outcomes." (PMID 39434688, 2024). "METTL16 and METTL3 were identified as key m6A regulators associated with improved prognosis in pancreatic cancer patients (P<0.05)." (PMID 39434688, 2024). "In the present study, we found that METTL3 had a weak association with PD-L1 expression in pancreatic cancer patients." (PMID 36212476, 2022). "To confirm the association between METTL3 and PD-L1 in pancreatic cancer cells, we transfected METTL3 cDNA and shMETTL3 plasmids to BxPC-3 and PANC-1 cells." (PMID 36212476, 2022). "In pancreatic cancer, METTL3 deficient cancer cells are highly sensitive to gemcitabine, 5-fluorouracil, cisplatin and radiotherapy." (PMID 35022030, 2022). "A recent study revealed that cigarette condensate promoted METTL3 to increase m6A modification via NF-κB associated protein, which resulted in excessive oncogenic microRNA-25 maturation in pancreatic cancer cells." (PMID 34330301, 2021). "It has been reported that the m6A writer METTL3 is significantly overexpressed in pancreatic cancer and is linked to cancer aggressiveness and patient survival." (PMID 34239358, 2021). "Pancreatic cancer cells with METTL3 silencing are more susceptible to irradiation, gemcitabine, 5‐FU and L‐OHP, but cell morphology and proliferation are not affected." (PMID 33029866, 2020). "In pancreatic cancer, it has reported that the deposition of cigarette smoke condensate caused the hypomethylation of METTL3 promoter and induced METTL3 highly expressed." (PMID 33292652, 2020). "In summary, METTL3 is associated with therapeutic resistance and a potential therapeutic target for pancreatic cancer." (PMID 31810483, 2019). "Studies have shown that METTL3 loss in pancreatic cancer cells is linked to higher sensitivity to anticancer reagents, such as gemcitabine, 5-fluorouracil, cisplatin, and irradiation." (PMID 31757221, 2019). "Another recent study reported that METTL3 was associated with chemo- and radioresistance in pancreatic cancer cells." (PMID 30149601, 2018). "Subsequently, we investigated whether HMGB1 could alleviate the inhibition of ferroptosis caused by METTL3 in pancreatic cancer cells." (PMID 40495163, 2025). "In addition, METTL3 has also been reported to be involved in pancreatic cancer invasion and metastasis, and is significantly associated with chemotherapy and radiotherapy resistance." (PMID 37936074, 2023).
pancreatic cancer (continued). "Since cigarette smoking is linked to pancreatic cancer, a study found that cigarette smoke condensate can increase expression of METTL3 by causing DNA hypomethylation of the METTL3 promoter, thus allowing the transcription factor NFIC to activate METTL3 transcription." (PMID 36008936, 2022). "In addition, METTL3 is associated with drug resistance of seminoma and pancreatic cancer." (PMID 34514103, 2021). "Experimental studies have shown that downregulation of Mettl3 leads to reduced cell proliferation, invasion, and migration in pancreatic cancer." (PMID 41517663, 2026). "In pancreatic cancer, Mettl3 contributes to proliferation, metastasis, and therapeutic resistance, identifying it as a promising biomarker, although its clinical specificity requires further validation." (PMID 41517663, 2026). "Mettl3 plays a crucial role in RNA m6A modification in pancreatic cancer and is involved in the positive regulation of pancreatic cancer cell proliferation and migration." (PMID 41517663, 2026). "In order to clarify the role of METTL3 in the progression of pancreatic cancer, we established stable knockdown and overexpression models of METTL3 in two pancreatic cancer cell lines: PANC1 and BXPC3." (PMID 40495163, 2025). "First, we quantified the expression of EMP1, IGF2BP3 and METTL3 in cell subpopulations of pancreatic cancer by analyzing single-cell sequencing data." (PMID 41285728, 2025). "METTL3 mediates m6A modification of exonuclease DCLRE1B to promote the development of pancreatic cancer (PC)." (PMID 41256854, 2025). "The results showed that knockdown of METTL3 inhibited the migration and invasive ability of pancreatic cancer cells, and overexpression of METTL3 would have an effect on the promotion of pancreatic cancer cell migration and invasive ability." (PMID 41285728, 2025). "It has been demonstrated in pancreatic cancer that cigarette smoke condensation induces hypomethylation of the METTL3 promoter, followed by recruitment of the transcription factor NFIC to induce METTL3 overexpression and promote cancer progression." (PMID 40830264, 2025). "For example, METTL3 stimulates the growth, invasion, and migration of pancreatic cancer cells both in vitro and in vivo." (PMID 40271153, 2025). "Here, we demonstrate that the cellular protein METTL3, which was previously shown to promote pancreatic cancer cell proliferation, invasion, and resistance to chemotherapy, plays a positive role in OV replication in most of the tested human PDAC cell lines." (PMID 40214229, 2025). "We observed that elevated levels of METTL3 in invasive pancreatic cancer provided a general m6A modification motif for RNA." (PMID 41285728, 2025). "Compared to the human pancreatic ductal epithelial cell line HPDE6C7, METTL3 expression was notably upregulated in multiple pancreatic cancer cell lines." (PMID 40175350, 2025). "To investigate the impact of METTL3 expression on the prognosis of pancreatic cancer patients, we utilized the PanCanSurvPlot database and observed that patients with high METTL3 expression exhibited a poor prognosis." (PMID 40495163, 2025). "In pancreatic cancer cells, METTL3 regulated ferroptosis and lipid peroxidation levels through SLC7A11." (PMID 40175350, 2025). "In pancreatic cancer, it has also been proven that METTL3 modulates ID2 by m6A methylation to regulate pancreatic cancer cell stemness." (PMID 40495163, 2025). "METTL3 is significantly upregulated in pancreatic cancer tissues compared to paracancerous normal tissues, and its upregulation is highly associated with advanced pathological stages." (PMID 40175350, 2025). "METTL3 is upregulated in pancreatic cancer, and knockdown of METTL3 in a mouse xenograft model suppressed cancer growth." (PMID 40448344, 2025). "The m6A methyltransferase METTL3 was also observed to act as a promoter in pancreatic cancer, which accelerated the proliferation and invasion of tumor cells." (PMID 40069867, 2025).
pancreatic cancer (continued). "We collected multiple samples of pancreatic cancer tissues along with adjacent normal tissues and detected an upregulation in METTL3 expression in tumor tissues through qPCR analysis." (PMID 40495163, 2025). "Taken together, these results revealed that TRIM21 increased PD-L1 expression and significantly enhanced antitumor immunity to impede tumor progression via regulating METTL3 in pancreatic cancer." (PMID 40175350, 2025). "In pancreatic cancer, METTL3 plays a crucial role in promoting tumor progression and is positively correlated with poor prognosis." (PMID 40175350, 2025). "Considering that TRIM21 functions as an E3 ligase, we analyzed the polyubiquitination of endogenous METTL3, which was further enhanced in pancreatic cancer cells treated with the proteasome inhibitor MG132." (PMID 40175350, 2025). "Our findings demonstrate that elevated expression of METTL3 in pancreatic cancer is partially dependent on O-GlcNAcylation, which is mediated by OGT." (PMID 40495163, 2025). "We next investigated the effects of TRIM21 promotes ferroptosis by targeting METTL3 as an intervention for pancreatic cancer progression in vivo." (PMID 40175350, 2025). "In this study, we investigated the molecular mechanism underlying the role of METTL3, an M6A WRITER, in pancreatic cancer development and its impact on gemcitabine sensitivity." (PMID 40495163, 2025). "Given that cell pluripotency has been linked to GEM resistance, we further investigated the impact of METTL3 on pancreatic cancer stemness." (PMID 40495163, 2025). "In summary, these results indicated that METTL3 was significantly upregulated and positively correlated with histological grade and poor prognosis in pancreatic cancer." (PMID 40175350, 2025). "In pancreatic cancer with proteasome inhibition by celastrol, METTL3 expression is decreased, m6A levels of Claspin and Bcl‐2 mRNA are lowered, and their expressions are suppressed by YTHDF3 binding, resulting in suppression of cell growth." (PMID 40448344, 2025). "We found that METTL3 is highly expressed in pancreatic cancer and regulates ferroptosis and gemcitabine resistance by promoting the degradation of HMGB1 in an m6A-YTHDF2-dependent manner." (PMID 40495163, 2025). "Studies in chicken liver cancer, mouse myoblasts, pancreatic carcinoma, and human liver cells have noted that quercetin acts as a METTL3 inhibitor, decreasing m6A levels." (PMID 40572597, 2025). "In pancreatic cancer, cigarette smoke condensates induce hypomethylation of the METTL3 promoter, which subsequently recruits the transcription factor NFIC for overexpression." (PMID 38166703, 2024). "LncRNA MALAT1 modulated METTL3-mediated PD-L1 expression and affected immune infiltrates in pancreatic cancer." (PMID 38638430, 2024). "Studies have demonstrated that METTL3 expression is upregulated in various tumors, including breast, lung, liver, stomach, colorectal, and pancreatic cancers.In PCa, METTL3 upregulation appears to play an important role." (PMID 38166703, 2024). "In pancreatic cancer, METTL3 modulates the MAPK pathway to enhance the resistance of pancreatic tumors to chemotherapy and radiotherapy." (PMID 39160604, 2024). "There is another report indicates that METTL3-mediated M6A modification involves in the prognosis and IR-induced alteration of cell cycle progressing of pancreatic cancer cells by targeting PLK1 mRNA 3’UTR." (PMID 38473842, 2024). "Knocking down METTL3 expression in pancreatic cancer cell lines enhances their sensitivity to anticancer radiotherapy and chemotherapeutics such as gemcitabine, cisplatin, and 5-fluorouracil." (PMID 38856795, 2024). "In pancreatic cancer, METTL3 increases the stability of lncLIFR-AS1 and indirectly promotes VEGFA expression." (PMID 39098905, 2024). "Our findings also confirm that the suppression of METTL3 leads to reduced stability of lncRNA-FOXD1-AS1 mRNA in pancreatic cancer cells." (PMID 38167126, 2024).
pancreatic cancer (continued). "As to the predicted immune functions of ITGB1, it has been proven to promote immune escape in pancreatic cancer under the regulation of METTL3-mediated N6-methyladenosine (m6A) modification." (PMID 38814534, 2024). "METTL3 is also an effective target for improving conventional treatment efficacy in patients with pancreatic cancer." (PMID 38856795, 2024). "In pancreatic cancer, METTL3 modulates the MAPK cascade to increase the resistance of pancreatic cancer cells to chemotherapy and radiotherapy." (PMID 37264402, 2023). "METTL3 was discovered to be expressed at high levels in pancreatic cancer databases, according to our research, including GSE15471 and GSE71989 datasets." (PMID 37936074, 2023). "We subsequently studied how DDX23 affected GEM resistance of pancreatic cancer in a METTL3-dependent manner." (PMID 36977668, 2023). "We demonstrated that celastrol treatment reduced total RNA m6A modification in pancreatic cancer cells by down-regulating METTL3 expression, especially decreased Claspin and Bcl-2 mRNA m6A modification, which induced the Claspin and Bcl-2 mRNA decay." (PMID 38110764, 2023). "A previous study indicated that METTL3 was upregulated in pancreatic cancer tissues compared with the cancer-adjacent tissues." (PMID 36977668, 2023). "Previous studies have shown that cigarette smoke condensate induces hypomethylation of the METTL3 promoter and, subsequently, recruitment of the transcription factor NFIC to induce METTL3 overexpression in pancreatic cancer." (PMID 36550779, 2023). "The expression of methyltransferase-like 3 (METTL3), the key enzyme involved in m6A methylation, in pancreatic cancer tissues was detected using a Western blot." (PMID 37998732, 2023). "We herein, for the first time identified DDX23 to be a direct target of METTL3 and an oncogene in pancreatic cancer." (PMID 36977668, 2023). "In pancreatic cancer (PC) cells, depletion of METTL3 decreases the expression of LINC00857, a long non-coding RNA, which promotes apoptosis in PC cells." (PMID 37015927, 2023). "Based on the findings in our study, we concluded that METTL3 regulated pancreatic cancer phenotypes by modifying its direct target DDX23 mRNA, thus PI3K/Akt signaling." (PMID 36977668, 2023). "Despite the increased number of published studies regarding the role of m6A modification mediated by METTL3 in cancer, it is still of great need to obtain a deeper insight into the role of METTL3 in pancreatic cancer." (PMID 36977668, 2023). "Depletion of METTL3 in pancreatic cancer cells lead to higher sensitivity to a series of anticancer therapy including irradiation (IR)." (PMID 36810281, 2023). "The knockdown of METTL3, an m6A methyltransferase, suppressed pancreatic cancer malignancy and gemcitabine resistance by regulating its direct target DDX23 mRNA, thus PI3K/Akt signaling." (PMID 36977668, 2023). "This study found the significantly upregulated METTL3 in pancreatic cancer, and METTL3 direct target DDX23 mRNA and promotes its translation in a YTHDF1-dependent pathway." (PMID 36977668, 2023). "In mammals, deletion of METTL3 facilitates intron retention mouse embryonic stem cells and RNA splicing in pancreatic cancer." (PMID 37015927, 2023). "Moreover, we uncovered that overexpression of METTL3 partially reversed celastrol-induced downregulation of Claspin and Bcl-2, which provided the causative link between RNA m6A modification and the expression of Claspin and Bcl-2 induced by celastrol treatment in pancreatic cancer cells." (PMID 38110764, 2023). "The inhibition of the METTL3 enhanced the sensitivity of pancreatic cancer cells to chemotherapy, especially to cisplatin, gemcitabine, and 5-FU, by inhibiting mitogen activated protein kinase (MAPK) signaling." (PMID 36835633, 2023).
pancreatic cancer (continued). "In pancreatic cancer, METTL3 modulates the MAPK cascade to increase the resistance of pancreatic cancer cells to chemotherapy and radiotherapy, while knockdown of METTL3 enhances the radiosensitivity of pancreatic cancer cells." (PMID 37264402, 2023). "In the current study, we demonstrated the downregulation of METTL3 and decrease of the global RNA m6A levels in celastrol-treated pancreatic cancer cells." (PMID 38110764, 2023). "In this study, we found that the inhibition of METTL3 increased the sensitivity of pancreatic cancer cells to GEM." (PMID 36977668, 2023). "The m6A methyltransferase METTL3 was found to be upregulated in GEM-resistant pancreatic cancer cell lines, and its silence led to suppressed cancer cell proliferation and resistance to GEM." (PMID 36977668, 2023). "METTL3 was also found upregulated and oncogenic in pancreatic cancer, demonstrated by promoting cell proliferation and invasion." (PMID 36977668, 2023). "In pancreatic cancer patients, METTL3 was shown to correlate withhigher stage and low survival rates, with both METTL3 mRNA and proteinlevels being higher in cancer cells compared to normal cells." (PMID 36692498, 2023). "For instance, METTL14 inhibits autophagy in testicular tissues and pancreatic cancer, whereas METTL3 promotes autophagy in the heart, liver, and endothelial cells." (PMID 36632456, 2023). "For example, METTL3 can regulate MAPK cascades to promote chemoresistance in pancreatic cancer cells." (PMID 36202872, 2022). "Taken together, lncRNA MALAT1 is involved in METTL3-mediated promotion of PD-L1 expression in pancreatic cancer." (PMID 36212476, 2022). "METTL3-depleted pancreatic cancer cells show higher sensitivity to anticancer reagents and irradiation." (PMID 36008936, 2022). "Taken together, METTL3 regulates the expression of PD-L1 partly due to regulation of lncRNA MALAT1 in pancreatic cancer." (PMID 36212476, 2022). "This study revealed that METTL3 regulated cell cycle, especially mitosis, through the methylation of those genes in pancreatic cancer cells, and PLK1 was identified as a gene playing a central role in this process." (PMID 35773310, 2022). "Inhibition of METTL3 enhances the sensitivity of pancreatic cancer cells to chemotherapy and radiotherapy." (PMID 35255776, 2022). "As of now, the clinical significance of METTL3 expression in human pancreatic cancer (PC) tissues still remains to be understood." (PMID 36058919, 2022). "Pancreatic cancer with downregulated METTL3 expression is reported to be sensitive to anticancer drugs and radiotherapy." (PMID 35813476, 2022). "In pancreatic cancer, METTL3 protein and mRNA levels are significantly increased, which promote cell proliferation, invasion and migration." (PMID 35628460, 2022). "METTL3 expression and RNA m6A modification is higher in pancreatic cancer tissues compared to normal tissues and high METTL3 expression is related to high pathological stage and high lymph node metastasis." (PMID 36008936, 2022). "We observed that overexpression of METTL3 increased the expression of PD-L1, whereas shMETTL3 infection led to downregulation of PD-L1 in pancreatic cancer cells." (PMID 36212476, 2022). "Depleting METTL3 from cells induced resistance to cisplatin, gemcitabine, and 5-fluorouracil in pancreatic cancer and non-small cell lung cancer." (PMID 35186927, 2022). "Cigarette smoke promotes the development and progression of pancreatic cancer via the METTL3/miR-25-3p/PHLPP2/AKT regulatory axis." (PMID 35155557, 2022). "In pancreatic cancer, METTL3-depleted cancer cells show higher sensitivity to gemcitabine, 5-FU and cisplatin." (PMID 35022030, 2022). "The role of METTL3 in pancreatic cancer development should be validated in animal study and clinical tissue samples." (PMID 36212476, 2022). "METTL3 expression increases resistance to the chemotherapeutic agents 5-fluorouracil, gemcitabine, and cisplatin in pancreatic cancer, through activation of the MAPK signaling pathway." (PMID 35327975, 2022).